LAG3 (lymphocyte activating 3)
Diseases named in the same sentence as LAG3 in open-access papers (continued):
Sharing a sentence is not in itself a finding about the gene and the disease.
tumor (continued). "Treatment with Tim-3, PD-1, and Lag3 antibodies resulted in higher cytotoxic activity of infiltrating CD8+ T cells, tumor regression and higher survival in MC38 tumor-bearing mice." (PMID 33585561, 2020). "Clinicopathological variables were stratified base on the tumor expression of CD163, PD-1, and LAG-3." (PMID 32756500, 2020). "The use of mAbs against LAG-3 interferes with the interaction of LAG-3 between tumor and/or immune cell that express MCH II molecules and promotes tumor cell apoptosis." (PMID 33167514, 2020). "As expected, in late stages of tumor growth, T cells upregulated exhaustion markers in late tumors (PD1 and Lag3)." (PMID 32433953, 2020). "Many inhibitory co-receptors including CTLA-4, PD-1, Tim-3, Lag-3, Tigit, CD160, Vista, and 2B4 have been identified, the expression of which are upregulated in different tumor microenvironments." (PMID 31511513, 2019). "Lymphocyte activation gene-3 (LAG-3) is an immune checkpoint, largely expressed in the tumor microenvironment of cHL." (PMID 31096713, 2019). "On activated Treg, LAG-3 expression becomes upregulated facilitating robust interaction with MHC II on DCs, further promoting suppression of the anti-tumor response in the TME." (PMID 31681327, 2019). "Anti-LAG-3 antibodies prevent binding of LAG-3 with its ligands, blocking these effects and thereby facilitating increased anti-tumor activity." (PMID 31640266, 2019). "Up-regulation of immune checkpoint molecules (PD-1, PD-L1, CTLA-4, TIM-3, Lag-3, TIGIT, CD73, VISTA, B7-H3) in the tumor microenvironment is an important mechanism that restrains effector T cells from the anti-tumor activity." (PMID 30863404, 2019). "Tumor-cell-extrinsic mechanisms include increased recruitment and activity of inhibitory immune cells within the TME and upregulation of LAG-3, TIM-3, and other inhibitory ligands." (PMID 31640266, 2019). "Both LAG3 and TIM3 are frequently found to be co-expressed with PD-1 on inactive TILs and dual ICB managed to effectively reverse tumor specific T cell anergy more than monotherapy in preclinical models." (PMID 30621125, 2019). "In the current analyses, we characterized the immunohistochemical expression of PD-1, PD-L1, LAG-3 and TIM-3 in tumor cells and TILs in a cohort of untreated DLBCL patients and correlated their expression with pathologic and clinical features." (PMID 31007846, 2019). "In mouse models, the immunosuppressive or anti-tumor roles of IL-35 have been linked to its ability to induce the expression of IL-10 and the immune checkpoints LAG3, TIM3, and PD1 in T cells, leading to T cell exhaustion and decreased anti-tumor immunity." (PMID 31316915, 2019). "LAG-3 is known to downregulate T-cell responses via interaction with major histocompatibility complex class-II (MHC-II), present on tumor cells or antigen-presenting cells like DCs." (PMID 31569553, 2019). "LAG3-/-/PDCD1-/- double knockout mice have also shown enhanced clearance of and survival from multiple transplanted tumor types." (PMID 31007846, 2019). "Eight potential classifiers were studied including CR, clinical stage of tumor at the time of diagnosis, CD8 density, PDL-1 status, CXCL9, IDO1, LAG3, and TIM3." (PMID 31360303, 2019). "Also, LAG3 blockade inhibits the suppressive activity of Treg cells both in vitro and in vivo in a model of autoimmune pulmonary vasculitis, thus raising the intriguing hypothesis that a similar beneficial effect may be obtained in the tumor microenvironment." (PMID 31623599, 2019). "We found increased expression of PD-1 and Tim-3 in all OS tumours and increased expression of LAG-3 in the majority of tumours, whereas CTLA4 had increased expression in fewer tumours." (PMID 30674975, 2019). "Upon evaluation of the tumor infiltrating CD8+ T cells we discovered co-expression of two inhibitory receptors, PD-1 and Lag-3, that were specific to tumors established during involution." (PMID 31244852, 2019).
tumor (continued). "We found that MIR155HG was significantly associated with immunological checkpoint blocking molecules PD‐1, PD‐L1, CTLA4, LAG3, and TIM3 in many tumors, and some of those types of tumor have better reactivity against immunological checkpoint blockade." (PMID 31568700, 2019). "Tumors with high T-cell signatures from our clustering analysis are concordant with high expression of PD-L1, PD-L2, PD-1, CD80, CD86, CTLA-4, Tim-3, LAG3, 4-1BB, CD8, and CD4, EBV-positive status, and low tumor purity and high immune score." (PMID 30911684, 2019). "Co-targeting the inhibitory receptor LAG-3 or the activating receptor ICOS on the TAI cells further enhanced this subset and resulted in improved tumor immunity." (PMID 31412943, 2019). "Currently, monoclonal antibody-based high affinity checkpoint inhibitors are tested against PD1 (nivolumab; lambrolizumab; pidilizumab, pembrolizimab, MGD013), LAG-3 (MGD013), and TIM-3 (lirilumab) to support anti-tumor activity of T cells." (PMID 30420856, 2018). "Other studies have found that blockade of PD-1 increased the expression of other immune checkpoint molecules on tumor-infiltrated immune cells, including Tim-3, CTLA-4, and LAG-3." (PMID 30309387, 2018). "Reductions in tumor NK (CD49+) cells and increase in T-cell exhaustion (LAG3+) were also observed during the active dosing period (data not shown)." (PMID 29755109, 2018). "The ImmunoINTEL panels were complemented with drop-in IMR and IMR-L markers (PD1/PDL1, TIGIT/CD112-CD155, TIM-3/Galectin-9, SIRPa/CD47, LAG-3/HLADR) to profile the functional status of TILs, and to study the cytotoxic potential of tumor TILs." (PMID 30400835, 2018). "On-treatment biopsies showed that Pegilodecakin increased GzmB+, Phospho-Stat3+ and Lag-3+ CD8+ T cells and HLA-A expression in the tumor." (PMID 30400835, 2018). "T-cell exhaustion plays an important role in the tumor microenvironment (TME) of FL and expression of exhaustion markers, such as PD1, TIM3 and LAG3, correlates with poor outcomes." (PMID 30400822, 2018). "Drake and collaborators originally reported that in PCa, tumor-specific CD4+ and CD8+ T cells rapidly upregulate LAG-3 upon in vivo antigen encounter." (PMID 30108594, 2018). "All compartments of MSI-H cancers, including tumour-infiltrating lymphocytes (TIL), stroma, and invasive front express many of these molecules, e.g., CTLA4, PD-1, PD-L1, LAG-3, and IDO." (PMID 30173350, 2018). "Analysis of expression of the checkpoint proteins at the RNA level in the LS-CRC tumour indicated low expression of all the markers, including PD1, PD-L1, CTLA-4, TIM3 and LAG3 (FPKM values <1)." (PMID 30108227, 2018). "Another potential ligand for LAG-3 is LSECtin, a member of the DC-SIGN family that is expressed on many tumors and is involved in the inhibition of anti-tumor T cell responses." (PMID 30250471, 2018). "LAG-3 expression increases in CAR-T cells upon antigen engagement of target and in the tumor microenvironment after CAR-T therapy." (PMID 29364163, 2018). "Tumor bearing mice were administered anti-CTLA-4, anti-PD-1, anti-PD-L1, anti-OX40 or anti- LAG3 twice weekly for 3 weeks." (PMID 30400822, 2018). "The immune phenotypes of the patients’ tumor milieu demonstrated overexpression of multiple checkpoint blockade markers including PD-L1 (6.9%), PD-L2 (10.9%), CTLA4 (3%), LAG-3 (8.9%), TIM-3 (9.9%) and VISTA (15.8%)." (PMID 30400835, 2018). "Tumor-infiltrating Tregs are featured in the enhancement of accumulation of forkhead box P3 (Foxp3) together with inhibitory molecules such as PD-1, CTLA-4, LAG-3, and TIM-3 during tumor progression." (PMID 30603054, 2018). "Taken together, the frequency of heavily exhausted T cells (PD-1+LAG-3+) in the population of peripheral CD4+ and CD8+ T cells increases in BLV-infected cattle bearing tumor." (PMID 29914540, 2018).
tumor (continued). "Targeting LAG-3 with antagonistic mAbs interferes with the LAG-3 interaction between MCH II molecules expressed by tumor and/or immune cells, promoting tumor cell apoptosis." (PMID 29544515, 2018). "This is in part due to the upregulation of several inhibitory receptors like PD-1, LAG3, TIGIT, and CTLA-4 that desensitize T cells to tumor antigens." (PMID 29482595, 2018). "PD-1, CTLA-4, TIM-3, LAG-3, TIGIT immune checkpoints and PD-L1, and galactin-9 ligands were selected due to their important role in tumor immune evasion and their potential as therapeutic targets for immune-mediated therapies." (PMID 30081950, 2018). "Treatment with anti-LAG-3 mAbs enhanced the number and effector function of tumor-specific CD8+ T cells in TRAMP mice, and delayed tumor growth." (PMID 30108594, 2018). "T cells in the tumor microenvironment (TME) of DIO mice demonstrated features of exhaustion, including significantly increased expression of PD-1, Tim3 and Lag3, but decreased expression of Ki67." (PMID 30400822, 2018). "Further exploitation of genome editing technologies to improve CAR-T cell anti-tumor activity include knockout of PD1, CTLA-4, TIM-3, and LAG-3." (PMID 30420856, 2018). "Anti-PD-1 and anti-LAG-3 synergized in the ID8-OT-I murine model to prolong survival, reduce tumor burden, and reduce Tregs, while increasing CD4+ and CD8+ TILs." (PMID 30049987, 2018). "To check the DNA epigenetic modifications in immune checkpoints/ligand in the breast TME, we examined the promoter CpG methylation profile of genes including PD-1, CTLA-4, TIM-3, LAG-3, PD-L1, and TIGIT in tumor and normal tissues." (PMID 29983831, 2018). "PD-1 and LAG-3 have been reported to be extensively co-expressed on CD4+, CD8+ T cells and particularly tumor-infiltrating T cells." (PMID 30603054, 2018). "LAG-3 was also shown to interact with LSECTin, a surface lectin of the DC-SIGN family which is expressed on dendritic cells and also on tumor tissue." (PMID 28073373, 2017). "In a murine model, LAG-3 has been shown to mediate tumour immune-escape through tolerance, and synchronous knock-out of LAG-3 and PD-1 confers resistance to tumour xenografts." (PMID 28423678, 2017). "The global proportion of PD-L1+, PD-L2+, LAG3+, and TIM3+ tumor-infiltrating lymphocytes (TIL) was low and detectable in only a small number of tumors." (PMID 29163490, 2017). "For example, LAG-3 and TIM-3 are commonly co-expressed with PD-1 on tumor-infiltrating T cells and work synergistically to regulate immune functions, suppressing the proliferation of T cells and the production of cytokines such as IL-2, TNF, and IFN-γ." (PMID 27756892, 2017). "For example, in the context of tumours, exhausted T cells express a whole set of inhibitory receptors with likely irredundant functions, such as CTLA4, TIM3, LAG3, TIGIT and others." (PMID 28537896, 2017). "PD-L1, LAG3, and TIM3 were also expressed on stromal and other immune cells in the tumor microenvironment." (PMID 29163490, 2017). "PD-1 and LAG-3 are co-expressed on dysfunctional or exhausted virus-specific CD8+ T cells, and on both CD4+ and CD8+ tumor infiltrating lymphocytes (TILs) in animal models of cancer." (PMID 28545567, 2017). "MSI-Hi CRCs were shown to upregulate expression of several immune checkpoints (PD-1, PD-L1, CTLA-4, LAG-3, IDO) in the TILs, stroma, or tumor invasive front compartments, enabling the tumor cells to survive." (PMID 28434400, 2017). "The major ligands of LAG-3 are class II MHC molecule on APCs and liver and lymph node sinusoidal endothelial cell C-type lectin (LSECtin) on tumor cells or hepatocytes." (PMID 28482851, 2017). "In fact, a core set of inhibitory receptors, including PD-1, LAG-3,Tim-3, and the T cell immunoglobulin and ITIM domain (TIGIT, also known as Vstm3 and WUCAM), is also expressed on tumor-infiltrating lymphocytes (TILs)." (PMID 28545567, 2017).
tumor (continued). "Concomitant delivery of the vaccine with monoclonal antibodies (mAbs) targeting immune checkpoint regulators LAG-3, PD-1 or PD-L1 demonstrated that the combination of vaccine with anti PD-1 mAb could significantly delay tumour growth and increase overall survival of tumour-bearing mice." (PMID 28537896, 2017). "A variety of other combinations with immune inhibition [such as with LAG-3, TIM-3, BTLA, etc.], chemotherapeutic agents and irradiation—as additive or designed to make a tumor more “antigenic”, etc., are in the drawing board." (PMID 28497159, 2017). "CD8+ T cells isolated from tumor-infiltrated lymph nodes (TILNs) were enriched in CTLA-4, CD160, 2B4, LAG-3, PTGER4, and PD-1 compared to their peripheral blood-derived counterparts." (PMID 29033936, 2017). "LAG-3 itself can directly modulate the activity of PD-1+ T cells and the synergy between LAG-3 and PD-1 can potentiate the tumor-induced tolerance." (PMID 28404974, 2017). "LAG-3 is highly co-expressed with other immune inhibitory molecules, including TIM-3, PD-1, 2B4 and T-cell immunoglobulin and ITIM domain (TIGIT), on tumor-specific CD4+ effector T cells." (PMID 28404974, 2017). "Upon Lag-3 blockade, CD8+ T cells exhibited restored effector function and accumulated at greater numbers in tumor tissue." (PMID 27314056, 2016). "In order to find promising targets in diverse cancer types, we examined how tumor-infiltrating immune cells correlate with inhibitory molecules, including the receptors CTLA4, PD-1, LAG3, and TIM3, and the ligands PD-L1/2, B7-H3/4." (PMID 27549193, 2016). "In our SCC tumor model, CD8+ TILs not only expressed a high level of PD-1 or LAG-3 but also predominantly co-expressed both inhibitory receptors." (PMID 27835902, 2016). "Wt B6 mice were inoculated with KRS-SCCs, treated with anti-PD-1 and anti-LAG3 antibodies or PBS control, and tumor growth was monitored for 2–3 weeks." (PMID 27835902, 2016). "In particular, LAG-3 is important for the suppressive functions of CD4+ Tregs in autoimmune responses, and for maintaining tolerance to self and tumor antigens via dampening the activity of antigen-specific CD8+ T cells." (PMID 27835902, 2016). "Low and high levels of LAG-3 and ICOS in each cell were scored using the median level of tumor infiltration by IC as a cut-off value." (PMID 27841362, 2016). "While circulating tumor-specific T cells exhibited normal effector function, TILs isolated from the tumor-draining lymph node (TDLN) showed a markedly exhausted phenotype, characterized by decreased IFNγ expression and upregulation of CTLA-4 and Lag-3." (PMID 27314056, 2016). "Combining MVA-BN-HER2 immunotherapy with PD-1 blockade resulted in high LAG-3 expression on CD8 T cells and CD8 T cell infiltration throughout the tumor and co-localization of CD4 and LAG-3 in patches of the tumor." (PMID 26910562, 2016). "Our data showed that majority of CD8+ TILs co-expressed PD-1 and LAG-3, which likely rendered CD8+ T cells incapable of mounting effective anti-tumor immune responses." (PMID 27835902, 2016). "Since our goal is to generate human iPSCs which can differentiate into patient's tumor-reactive CD8+ T cells for immunotherapy, we measured cell surface expression of inhibitory receptors, PD-1, TIM-3, and LAG-3." (PMID 27057178, 2016). "In accordance with the findings from the mRNA sequencing data, TIM-3, LAG-3 and CTLA-4 were expressed at higher levels in both CD4 and CD8 T cells from PD-1 resistant as compared with untreated EGFR TL tumours by flow cytometry analysis." (PMID 26883990, 2016). "Moreover the presence within the tumors of myeloid cells with the phenotype and functional activity of MDSCs, supports the hypothesis that the PD-1/PD-L1 and LAG-3/HLA class II interactions might be pivotal to the immune deviation in the tumor microenvironment." (PMID 26700461, 2016). "PD1, TIM3, BTLA, 2B4, LAG3 were markedly increased in both CD4+ and CD8+ T cells of B16F10 tumor-bearing mice compared to naive mice." (PMID 27447564, 2016).
tumor (continued). "Expression of the iRs PD-1, LAG-3, and TIM-3 correlated with antigen-experienced CD8+ TILs that recognized and lysed autologous tumor cell lines." (PMID 27314056, 2016). "Both spleen and bone marrow-derived CD4 and CD8 T cells showed a significant increase in tumor-specific IFN-γ producing cells when mice were treated with anti-PD-L1 in combination with anti-TIM-3, or anti-LAG-3 or anti-CTLA4 as compared to anti-PD-L1 alone." (PMID 25614821, 2015). "Dual antibody blockade or genetic knockout of LAG3 and PD1 significantly enhanced T effector function and delayed tumor growth." (PMID 26318293, 2015). "Remarkably, treatment with dual anti-LAG3/PD1 antibodies (4 doses at 200 μg per mouse, delivered every other day) resulted in tumor rejection in 100% of the mice." (PMID 26318293, 2015). "Although tumor cells, with rare exception of hematologic malignancies, do not express co-stimulatory molecules, they can express inhibitory molecules, such as PD-L1, PD-L2, LAG-3, TIM3, BTLA-4, or VISTA that induce deletion or anergy of tumor-reactive T cells." (PMID 26284197, 2015). "In summary, the study presented here indicates that LAG3 and PD1 collaborate to mediate T cell function and anti-tumor immunity." (PMID 26318293, 2015). "As for LAG-3, preclinical studies have shown co-expression of LAG-3 and PD-1 on tumor infiltrating cells." (PMID 26487966, 2015). "Checkpoint inhibitors (anti-CTLA4, anti-PD-1/anti-PD-L1, anti-LAG-3, anti-BTLA), as well as agonists of CD40 or TLR, are also known to improve anti-tumor T cell survival." (PMID 25325015, 2014). "Other co-inhibitory receptors, which can be exploited by tumors to dampen anti-tumor immune responses, are HVEM, ILT3 and 4, TIM-3, and LAG-3." (PMID 24348481, 2013). "Co-expression of LAG-3 and PD-1 on tumor-infiltrating CD8+ T cells, induced by either tumor-derived APCs or cytokines secreted in the tumor microenvironment, contribute to the establishment, and maintenance of an immunosuppressive tumor microenvironment." (PMID 24348481, 2013). "Based on published evidence indicating a therapeutic potentials in several tumor models we tested mAbs to CD137, CD40, CTLA-4, PD-1, TIM-3 and LAG-3, as single agents and in combinations." (PMID 24367702, 2013). "Since it is likely that many of those total CD8 T-cells from TILN are tumor specific, our data suggest that they frequently express inhibitory receptors such as CTLA-4, LAG-3, PD-1, TIM-3, BTLA and 2B4." (PMID 22347406, 2012). "For immune checkpoint inhibitors, a pre‐existing inflamed tumor microenvironment, characterized by high CD8+ tumor‐infiltrating lymphocytes and inflammatory gene signatures (e.g., CD8A, CD274, LAG3), correlates with improved survival with nivolumab and atezolizumab plus bevacizumab." (PMID 41509174, 2026). "In addition to reduced abundance, residual CD8+ cells often showed higher expression of exhaustion markers such as PD-1, LAG-3, and TIM-3, which entail a suboptimal cytotoxic response in the tumor microenvironment." (PMID 41562715, 2026). "LAG‐3 and PD‐1 are commonly coexpressed on CD8+ TILs, thus contributing to tumor‐mediated immune suppression, and blocking both receptors can synergistically reduce tumor growth and strengthen antitumor immunity." (PMID 41492362, 2026). "PD-1 and LAG-3 expression strongly correlated with CD8 and moderately correlated with TILs, indicating that checkpoint expression predominantly reflects an immune effector-engaged tumor microenvironment." (PMID 41828646, 2026). "During the process of in vitro expansion and repetitive stimulation, along with the high concentrations of inhibitory cytokines in the tumor microenvironment, CAR-T cells develop an exhausted phenotype (upregulation of PD-1, LAG3, TIM3, and TIGIT and decreased secretion of IL-2, TNF-α, and IFN-γ)." (PMID 40002679, 2025).